WBP11 (WW domain binding protein 11)
Description:
Activates pre-mRNA splicing. May inhibit PP1 phosphatase activity.
Synonyms: WBP-11; NpwBP; SIPP1; PPP1R165; BUG13; VCTERL; VCTRL
Tractability: Small molecule: a structure with a bound ligand is known. PROTAC: UniProt records ubiquitination sites on it; ubiquitination databases record sites on it; its protein half-life has been measured.
Gene: Protein-coding gene on chromosome 12 (14,784,582 to 14,803,500, reverse strand). Ensembl gene ENSG00000084463.
Subcellular location: Nucleus; Cytoplasm
Subcellular location (Human Protein Atlas): Nucleoplasm; Acrosome; Cytosol; End piece; Principal piece; Vesicles
Pathways (Reactome):
Disease: Dengue Virus-Host Interactions
Metabolism of RNA: mRNA Splicing - Major Pathway
Gene Ontology:
Molecular function: protein binding; RNA binding; WW domain binding; protein phosphatase regulator activity; single-stranded DNA binding
Biological process: RNA splicing; RNA processing
Cellular component: cytosol; nucleoplasm; nucleus; cytoplasm
Genetic constraint (gnomAD): Loss-of-function variants: 12 observed, 60.53 expected, observed/expected ratio (o/e) 0.2, 90% interval 0.13 to 0.32. The upper end of that interval is the gene's LOEUF score, 0.32, which puts it in group 1 of 6, group 1 being the genes least tolerant of losing a copy. Missense variants: 523 observed, 785.57 expected, observed/expected ratio (o/e) 0.67, 90% interval 0.62 to 0.72. Synonymous variants: 242 observed, 264.17 expected, observed/expected ratio (o/e) 0.92, 90% interval 0.82 to 1.02.
Homologues: Orthologues: chimpanzee WBP11 (99% identical), macaque WBP11 (99% identical), rabbit WBP11 (92% identical).
Diseases named in the same sentence as WBP11 in open-access papers:
WBP11 is named in the same sentence as 12 diseases in open-access papers, as found by Europe PMC text mining. Sharing a sentence is not in itself a finding about the gene and the disease. The quoted sentences say what the papers report.
gastric cancer (2 papers, 2021 to 2024). A primary or metastatic malignant neoplasm involving the stomach. "Similarly, WBP11 has been linked to the activation of the fibroblast growth factor receptor (FGFR)-Wingless/Integrated (Wnt)-β-catenin pathway in human gastric cancer." (PMID 38951817, 2024). "Interestingly, a study on gastric cancer found that inhibiting WBP11 expression results in the suppression of β‐catenin and thus suppression of proliferation and migration of tumor cells." (PMID 34309201, 2021). "In line with the findings in gastric cancer, analysis of the TCGA data showed that the expression levels of WBP11 in colon and rectum tumors were higher than in adjacent normal tissues." (PMID 34309201, 2021).
colorectal cancer (1 paper, 2021). A primary or metastatic malignant neoplasm that affects the colon or rectum. "We also detected the association of a set of SNPs that are highly linked with WBP11‐rs7314075 in the TCGA colorectal cancer cohort dataset, increasing our confidence in the association of this SNP with DSS." (PMID 34309201, 2021). "After adjustment for clinical covariates, one common SNP that locates in an intron of WBP11 (rs7314075) was significantly associated with the risk of death from colorectal cancer under both dominant (HR = 3.36; P‐value = 3.27 × 10−08) and additive (HR = 2.65; P‐value = 3.24 × 10−08) genetic models." (PMID 34309201, 2021). "Overall, findings by this study and existing literature suggest a possible biological relationship of WBP11 with disease outcomes in colorectal cancer, and the ERP27 gene can be an interest for future studies." (PMID 34309201, 2021). "Also, the tumor WBP11 expression levels were associated with CMS in the TCGA dataset, which is a gene expression‐based classification system and has been reported to have associations with outcomes in colorectal cancer." (PMID 34309201, 2021).
colorectal tumors (1 paper, 2021). "Interestingly, expression levels of ERP27 and WBP11 were significantly different between colorectal tumors and nontumor tissues." (PMID 34309201, 2021).
pemphigus (1 paper, 2025). Pemphigus is a group of rare autoimmune diseases that cause blistering of the skin and mucous membranes (mouth, nose, throat, eyes, and genitals).This conditioncan occur at any age, but often strikes people in middle or older age. "Differential expression analysis was conducted to investigate the expression patterns of the five genes (XBP1, FBXO45, SAT2, AIFM1, and ACSL4) and eight other DEGs associated with ferroptosis (G3BP1, WBP11, TET2, IRF8, FASN, GDPD5, H1-4, and HUWE1) in both the pemphigus and control groups." (PMID 40612574, 2025).
rectal tumors (1 paper, 2021). "Comparison of gene expression levels using the TCGA data showed that the expression levels of ERP27 and WBP11 were higher in the colon and rectal tumors than in adjacent normal tissues (the ‘solid tissue normal’ in TCGA data)." (PMID 34309201, 2021).
tumor (5 papers, 2016 to 2025). "WBP11 could affect tumor cell proliferation and metabolic reprogramming." (PMID 40406140, 2025). "When WBP11 is silenced, IR is restored, MCM7 expression is reduced, and tumor growth is suppressed, making WBP11 a potential therapeutic target." (PMID 40870034, 2025).
WBP11 also shares sentences with these, for which no sentence is quoted: cancer (2 papers); Macrocephaly (1); neurological diseases (1); pancreatic cancer (1); rectum (1); viral infection (1).